ANXA1 (annexin A1)
Diseases named in the same sentence as ANXA1 in open-access papers (continued):
Sharing a sentence is not in itself a finding about the gene and the disease.
nasal polyps (3 papers, 2010 to 2022). "With respect to Annexin A1, its expression has been investigated in normal and chronically inflamed nasal mucosa and nasal polyps of human subjects." (PMID 35563776, 2022). "In chronic inflammation, the expression of ANXA1 is also positively modulated in human epithelial cells in nasal polyps cases after treatment with glucocorticoids, suggesting an inhibitory role of ANXA1 in epithelial proliferation, which is common to this pathology." (PMID 22740770, 2012).
oesophageal adenocarcinoma (3 papers, 2008 to 2014). "In oesophageal adenocarcinoma, the tumour cell expression of annexin A1 has been associated with poor prognosis." (PMID 18071363, 2008).
pneumococcal pneumonia (3 papers, 2020 to 2022). A febrile disease caused by STREPTOCOCCUS PNEUMONIAE. "Of note, the treatment of pneumococcal pneumonia with the Annexin A1 peptide Ac2-26, a pro-resolving mediator, did not increase IL-10, while reducing the inflammatory response, lung damage, bacterial loads and increasing phagocytosis." (PMID 35159341, 2022).
psoriasis (3 papers, 2014 to 2023). An autoimmune condition characterized by red, well-delineated plaques with silvery scales that are usually on the extensor surfaces and scalp. "In this study, we analyzed serum levels of moesin, K17, STIP1, and ANXA1 in psoriasis patients and healthy controls, and measured the stainability of these proteins in psoriasis tissues." (PMID 25010044, 2014). "In this study, a total of 22 psoriasis-associated autoantigens, including moesin, K17, STIP1, and ANXA1, were identified employing 2D-IB with sera from patients with psoriasis." (PMID 25010044, 2014). "Furthermore, serum levels of moesin, keratin 17 (K17), annexin A1 (ANXA1), and stress-induced phophoprotein-1 (STIP1), which were detected as autoantigens, were studied by dot blot analysis with psoriasis patients and healthy controls." (PMID 25010044, 2014).
squamous cell lung carcinoma (3 papers, 2021 to 2022). A carcinoma arising from squamous bronchial epithelial cells. "The present study revealed that strong ANXA1 protein expression is significantly correlated to longer overall survival of patients with squamous cell lung cancer (SQCLC, n = 79) but not pulmonary adenocarcinoma (AC, n = 78)." (PMID 33959206, 2021).
steatosis (3 papers, 2014 to 2023). Increased lipid within the cytoplasm of cells. "Treatment of mice with recombinant ANXA1 reduces liver inflammation and fibrosis without affecting steatosis and metabolism, suggesting a possible mechanism by which Lal−/− mice attempt to combat liver inflammation." (PMID 37595802, 2023).
ulcers (3 papers, 2012 to 2013). "Gastric mucosal repair of acetic acid-induced ulcers is significantly impaired in AnxA1-deficient mice, whereas in wild-type littermates healing of the ulcer region is accompanied by an increase of AnxA1 at the ulcer margin." (PMID 22723974, 2012). "Our results showing the presence of copious numbers of neutrophils and larger ulcers in FPR1−/− mice may be related to a reduction in these anti-inflammatory activities of annexin A1, leading us to examine annexin A1 levels in the mice." (PMID 22383080, 2012). "Hence, a strain-specific lack of annexin A1 expression is unlikely to explain the exacerbation of ulcer formation or reduced re-epithelialization in FPR1−/−mice." (PMID 22383080, 2012).
acute aortic dissection (2 papers, 2022 to 2023). "Thus, AnxA1 deficiency in SMCs aggravates acute aortic dissection (AAD) in mice." (PMID 36313572, 2022). "AnxA1 plays an important role in maintaining SMCs homeostasis and protection against acute aortic dissection." (PMID 36313572, 2022).
acute lymphoblastic leukemia (2 papers, 2007 to 2009). Leukemia with an acute onset, characterized by the presence of lymphoblasts in the bone marrow and the peripheral blood. "Pleiotrophin (PTN) is up-regulated in human endometrial epithelial cells, and annexin A1 (ANXA1) is up-regulated in a lymphoblastic leukemia cell line." (PMID 19594897, 2009).
autism (2 papers, 2014 to 2025). Persistent deficits in social interaction and communication and interaction as well as a markedly restricted repertoire of activity and interest as well as repetitive patterns of behavior. "One variant upstream of the gene disrupts or creates binding sites for transcription factors such as the vitamin D receptor and OTX, which have been implicated in psychiatric disorders including autism, thus potentially modulating ANXA1 expression." (PMID 24720851, 2014). "The consequences of annexin A1 dysregulation could therefore influence multiple pathways, some of which have been previously linked to autism pathophysiology." (PMID 24720851, 2014). "In light of present day literature, these observations suggest that a low penetrance ANXA1 duplication may be associated with a broader autism phenotype and co-morbidities, with other unidentified factors interacting with the duplication to influence its phenotypic expression." (PMID 24720851, 2014). "Here, we characterize a small recurrent duplication in the annexin A1 (ANXA1) gene, identified by the Autism Genome Project (AGP) study." (PMID 24720851, 2014).
brain injury (2 papers, 2021 to 2023). Acute and chronic (see also brain INJURIES, CHRONIC) injuries to the brain, including the cerebral hemispheres, CEREBELLUM, and brain STEM. "In the present study, we concentrated on annexin A1 (ANXA1) as a novel regulator of endothelial function after traumatic brain injury." (PMID 33679307, 2021).
cerebral thrombosis (2 papers, 2021 to 2025). "Since targeting the AnxA1/FPR2 pathway can inhibit thromboinflammation and cerebral thrombosis, it is plausible that FPR2 and ANXA1 participate in thrombus evolution." (PMID 41464211, 2025). "Furthermore, targeting SCD neutrophils with a pro-resolution molecule Annexin A1(AnxA1)Ac2-26 resulted in decreased H3Cit+ NETs from SCD neutrophils and reduced cerebral thrombosis in sickle transgenic mice." (PMID 34944761, 2021).
coronary artery aneurysm (2 papers, 2023 to 2025). "Additionally, a study from China reported that decreased Annexin A1 levels are directly associated with coronary artery aneurysms." (PMID 38031949, 2023). "Even though there is a relationship between Annexin A1 and CRP, blood CRP levels are not directly correlated with coronary artery aneurysm development." (PMID 38031949, 2023).
coronary artery disease (2 papers, 2017 to 2019). "Here, we investigated the expression of AnxA1 in peripheral blood mononuclear cells (PBMCs) from patients with coronary artery disease (CAD)." (PMID 28329022, 2017).
cutaneous leishmaniasis (2 papers, 2021 to 2024). Leishmaniasis affecting the skin. "Expression of Annexin A1 (ANXA1), a protein implicated in exosome-mediated pathologies and viral internalization, has been shown to correlate with cutaneous leishmaniasis severity." (PMID 39076982, 2024). "Herein, we hypothesized that ANXA1 could be implicated in cellular events underlying leishmanial exosome-mediated exacerbation of cutaneous leishmaniasis." (PMID 39076982, 2024). "In summary, this study elucidates the role of the ANXA1/FPR axis in the exacerbation of cutaneous leishmaniasis mediated by leishmanial exosomes, whereby initial infection is enhanced and maintained over the course of infection, resulting in increased severity of disease." (PMID 39076982, 2024). "As FPR2 is an established downstream receptor of ANXA1, we aimed to assess the implication of the ANXA1/FPR2 receptor-ligand interaction in an in vivo model of experimental cutaneous leishmaniasis." (PMID 39076982, 2024). "Altogether, this suggests that the ANXA1/FPR2 interaction in myeloid cells is a key contributor to skin pathology and parasitemia during cutaneous leishmaniasis." (PMID 39076982, 2024).
ductal carcinoma in situ (2 papers, 2015 to 2024). "Others have reported decreased annexin A1 expression in ductal carcinoma in situ and invasive ductal carcinoma compared to normal and benign tissues." (PMID 26000884, 2015).
encephalitis (2 papers, 2022 to 2023). An acute inflammatory process affecting the brain parenchyma. "Furthermore, in HSV1 encephalitis in mice, the absence of AnxA1 or FPR2 was associated with reduced mortality and lower tissue viral loads compared to infected WT controls." (PMID 37190040, 2023).
eosinophilia (2 papers, 2019 to 2023). "Anxa1-/- mice exhibited significantly increased airway eosinophilia and elevated numbers of Th2 lymphocytes." (PMID 37227431, 2023). "Histological analysis revealed intense eosinophilia and mast-cell activation in AD animals, especially in AnxA1-/-." (PMID 30650525, 2019).
familial breast cancer (2 papers, 2015 to 2024). "The frequency of ANXA1 positive tumors was higher in familial breast cancer patients with BRCA1/2 mutations than in BCAC patients, with 48.6 % versus 12.4 %, respectively; P <0.0001." (PMID 26137966, 2015). "Patients with BRCA1 or BRCA2 (BRCA1/2) germline mutations often present tumors with these characteristics, but until now there are no data in the literature implicating a link between high ANXA1 expression and familial breast cancer." (PMID 26137966, 2015).
fungal infection (2 papers, 2022 to 2024). "The anti-inflammatory protein ANXA1 is mainly found in macrophages and neutrophils and is associated with inflammatory processes, immune infiltrates in cancer cells and immune response during fungal infections." (PMID 35748965, 2022). "ANXA1 appears to regulate the neutrophil response under fungal infection conditions, altering lipid membrane organization and metabolism." (PMID 39227786, 2024).
gastric ulcer (2 papers, 2014 to 2018). An ulcerated lesion in the mucosal surface of the stomach. "In conclusion,our results evidence that both the AnxA1 and Gal-1 anti-inflammatory proteins are overexpressed in precancerous gastric lesions such as intestinal metaplasia and gastric ulcer." (PMID 24719523, 2014). "The relative gene expression of ANXA1 was 6.2- and 6.7-fold increased, respectively, in intestinal metaplasia and gastric ulcer and these results were confirmed by AXNA1 protein expression analysis." (PMID 24719523, 2014). "Furthermore, this same group also demonstrated that hemorrhagic lesions were greater in AnxA1−/− mice upon induction of gastric ulcers." (PMID 29659553, 2018).
gestational hypertension (2 papers, 2022 to 2025). "Future experiments need to target the functional heterogeneity of ANXA1 in different disease types through conditional knockout technology to explain its paradoxical expression in specific models such as gestational hypertension." (PMID 41208642, 2025). "However, the role of ANXA1 can be context‐dependent, exhibiting both protective and detrimental effects in specific conditions such as gestational hypertension and transient ischemic attack." (PMID 41208642, 2025).
gingivitis (2 papers, 2022 to 2024). A disorder involving inflammation of the gums; may affect surrounding and supporting structures of the teeth. "However, among the pregnant subpopulations, women with gingivitis had significantly higher ANXA-1 and IL-1β levels than healthy pregnant women." (PMID 36432584, 2022). "When comparing ANXA-1 and IL-1β levels, Hassan and colleagues found that the pregnant gingivitis group exhibited nearly 2-fold higher ANXA-1 levels compared with the non-pregnant gingivitis group." (PMID 36432584, 2022).
glomerular diseases (2 papers, 2014 to 2022). "Measurement of urinary ANXA1 protein levels can help in differentiating MCD from other types of glomerular disorders." (PMID 24591769, 2014). "Importantly, only ANXA1, which is significantly increased in the kidney and urine, can be used as an early noninvasive urinary biomarker for most types of glomerular disorders." (PMID 24591769, 2014). "To determine whether ANXA1 could serve as a biomarker for noninvasive diagnosis and prognostic prediction, we measured urine protein levels in patients with various types of glomerular disorders and apparently healthy donors by Western blot analysis." (PMID 24591769, 2014). "We infer that ANXA1 and ANXA2 may play important pathogenic roles in glomerular disorders." (PMID 24591769, 2014). "We then examined ANXA1 and ANXA2 mRNA and protein expression in patients with various types of glomerular disorders by ISH or IHC staining." (PMID 24591769, 2014). "In the present study, we characterized the expression pattern and tissue distribution of ANXA1 and ANXA2 in the ADG model over time and confirmed these results in a large number of different types of human glomerular disorders." (PMID 24591769, 2014). "ANXA1 became detectable in the urine as early as day 7 in the ADG model and, importantly, was detectable in almost all urine samples from patients with glomerular disorders except those with MCD (less than 10.52% of cases were detected)." (PMID 24591769, 2014). "Although ISH showed that very little ANXA1 mRNA was expressed in the tubules or glomeruli in the normal controls (bottom line) and patients with MCD (top line), most biopsy tissues from other types of glomerular disorders were found to have high levels of ANXA1 mRNA in the glomeruli examined." (PMID 24591769, 2014). "However, the expression patterns and potential roles of ANXA1 and ANXA2 remain unclear in most glomerular disorders." (PMID 24591769, 2014).
heart failure (2 papers, 2020 to 2022). Inability of the heart to pump blood at an adequate rate to meet tissue metabolic requirements. "This is in line with recent work by Ferraro and co-workers, who demonstrated a functional link between AnxA1 and reparative macrophage phenotype in settings of heart failure, consequent to VEGF release from the immune cell." (PMID 32403233, 2020).
hepatopulmonary syndrome (2 papers, 2013 to 2015). Hepatopulmonary syndrome (HPS) is a lung disease characterized by widening of arteries and veins (dilatation) in the lungs in people who have chronic liver disease. "PMVECs were cultured from the normal rats and then divided into three groups(Ad-ANXA1-transfected group, a non-transfected group, and an adenovirus empty vector group) and incubated by nomal rat serum or hepatopulmonary syndrome rat serum respectively." (PMID 23587191, 2013). "Notably, we have previously reported that hepatopulmonary syndrome’s rat serum induces PMVECs to differentiate into PASMLCs, during which the TGF-β1/Smads signal and annexin A1/A2 proteins might play a key role in this differentiation and transformation of PASMLCs." (PMID 26664882, 2015).
idiopathic pulmonary fibrosis (2 papers, 2022). Idiopathic pulmonary fibrosis (IPF) is a nonneoplastic pulmonary disease that is characterized by the formation of scar tissue within the lungs in the absence of any known cause. "A study which supports this idea showed that in patients with idiopathic pulmonary fibrosis (IPF), ANXA1 was associated with increased CD4+ T‐cell activity, as well as autoantibody production in patients with exacerbated IPF." (PMID 35146757, 2022).
invasive breast carcinoma (2 papers, 2017 to 2020). A carcinoma that infiltrates the breast parenchyma. "Due to their tissue expression in invasive breast cancer, ANXA1 and FPR2 have become a target for drug discovery." (PMID 29263330, 2017). "Given that ANXA1 positively regulates the expression and function of MMP9 in invasive breast cancer, we believe that the sensitivity of MMP9 may be related to the effect of DCST1-AS1 on ANXA1." (PMID 32226772, 2020).
keloid (2 papers, 2017 to 2020). An irregularly shaped, elevated mark on the skin caused by deposits of excessive amounts of collagen during wound healing. "Therefore, our results indicate the role of AnxA1 in tissue repair in burns, both in epithelial regeneration as in the protection against keloid formation." (PMID 28278234, 2017). "However, the results of the present study revealed for the first time the downregulation of five genes (ANXA1, ASPN, IGFBP7, LGALS1, and PTN) which is in contrast to the upregulation of the same genes in African and Caucasian keloid samples." (PMID 32085797, 2020).
laryngeal squamous cell carcinoma (2 papers, 2014). A squamous cell carcinoma that arises from the larynx. "Our data showed that ANXA1 and dexamethasone inhibit the release of inflammatory cytokines by Hep-2 cells, which may prevent the development of laryngeal squamous cell carcinoma." (PMID 25490767, 2014). "However, no data are available regarding the role of ANXA1 and FPRs in laryngeal squamous cell carcinoma." (PMID 25490767, 2014).
leprosy (2 papers, 2020 to 2021). Leprosy is a chronic infectious disease affecting primarily the skin and peripheral nervous system. "This study identified the presence of MDSCs in patients with leprosy and its expression of ANXA1 to establish a possible default association in leprosy reactions." (PMID 34627197, 2021). "This is the first study describing the expression of ANXA1 in peripheral blood and skin tissue leukocytes of patients with leprosy." (PMID 33263684, 2020). "Previous studies have already demonstrated the ANXA1 expression in leukocytes of leprosy patients." (PMID 34627197, 2021). "Finally, to analyze a possible mechanism of action of MDSCs in patients with leprosy, the ANXA1 expression was analyzed." (PMID 34627197, 2021). "Myeloid-derived suppressor cell are present in leprosy patients and annexin A1 might be regulated the host response against Mycobacterium leprae." (PMID 34627197, 2021). "Thus, this work aimed to identify the presence of MDSCs and the protein ANXA1 in leprosy patients with clinical forms of leprosy and with T1R and T2R." (PMID 34627197, 2021). "In addition, in order to assess the activation of immune system homoeostasis mechanisms, we quantified the expression of ANXA1 in the peripheral blood, plasma, and tissue leukocytes of leprosy patients." (PMID 33263684, 2020). "In circulating monocytes, ANXA1 expression was similar in all clinical forms of leprosy." (PMID 33263684, 2020). "Thus, understanding the importance of endogenous anti-inflammatory ANXA1 in leukocyte regulation among leprosy patients can help prevent the worst outcomes in this disease." (PMID 33263684, 2020). "Finally, the ANXA1 levels were evaluated in the leprosy patients, which indicated an increase in the paracrine release of this protein in the LL patients compared to the HC group (p<0.001)." (PMID 33263684, 2020). "To understand the behavior of these mediators we quantified the expression of annexin-A1 (ANXA1) in the peripheral blood and plasma as well as tissue leukocytes in all clinical forms of leprosy and compared with healthy controls." (PMID 33263684, 2020).
leukemia (2 papers, 2024). A malignant (clonal) hematologic disorder, involving hematopoietic stem cells and characterized by the presence of primitive or atypical myeloid or lymphoid cells in the bone marrow and the blood. "γ-Mangostin effectively suppresses leukemia cells by inducing ICD, which is characterized by increased expression of HSP90B1, ANXA1, and IL1B." (PMID 38627685, 2024).
lung disease (2 papers, 2021). "Considering the clinical application of Annexin A1 on lung disease, it was speculated that Annexin A1 may be another new therapeutic treatment approach for patients with ARDS." (PMID 34008449, 2021).